MRPS24 (mitochondrial ribosomal protein S24)
Synonyms: MRP-S24; S24mt; bMRP47; HSPC335; bMRP-47
Tractability: Small molecule: a structure with a bound ligand is known. PROTAC: ubiquitination databases record sites on it; its protein half-life has been measured.
Target class: Other cytosolic protein
Gene: Protein-coding gene on chromosome 7 (43,866,557 to 43,869,893, reverse strand). Ensembl gene ENSG00000062582.
Subcellular location: Mitochondrion
Pathways (Reactome):
Metabolism of proteins: Mitochondrial ribosome-associated quality control; Mitochondrial translation elongation; Mitochondrial translation initiation; Mitochondrial translation termination
Gene Ontology:
Molecular function: RNA binding; structural constituent of ribosome
Biological process: mitochondrial translation
Cellular component: mitochondrion; mitochondrial inner membrane; mitochondrial small ribosomal subunit
Genetic constraint (gnomAD): Loss-of-function variants: 15 observed, 21.87 expected, observed/expected ratio (o/e) 0.69, 90% interval 0.46 to 1.06. The upper end of that interval is the gene's LOEUF score, 1.06, which puts it in group 4 of 6, group 1 being the genes least tolerant of losing a copy. Missense variants: 224 observed, 221.41 expected, observed/expected ratio (o/e) 1.01, 90% interval 0.91 to 1.13. Synonymous variants: 93 observed, 95.12 expected, observed/expected ratio (o/e) 0.98, 90% interval 0.83 to 1.16.
Homologues: Orthologues: chimpanzee MRPS24 (99% identical), pig MRPS24 (91% identical), dog MRPS24 (87% identical), guinea pig MRPS24 (84% identical), mouse Mrps24 (84% identical), tropical clawed frog mrps24 (62% identical), zebrafish mrps24 (59% identical), Drosophila melanogaster mRpS24 (38% identical), Caenorhabditis elegans mrps-24 (32% identical).
Diseases named in the same sentence as MRPS24 in open-access papers:
MRPS24 is named in the same sentence as 1 disease in open-access papers, as found by Europe PMC text mining. Sharing a sentence is not in itself a finding about the gene and the disease.
MRPS24 shares sentences with these, for which no sentence is quoted: infection (1 paper).